CTNNB1 (catenin beta 1)
Diseases named in the same sentence as CTNNB1 in open-access papers (continued):
Sharing a sentence is not in itself a finding about the gene and the disease.
endometrioid ovarian cancer (11 papers, 2015 to 2025). "Patients with CTNNB1 activating mutations accounted for up to 54% of all the endometrioid ovarian cancer patients." (PMID 35646632, 2022). "With respect to the ovary, CTNNB1 pathogenic variants have mainly been found in endometrioid ovarian cancers." (PMID 29124495, 2018). "Interestingly, mutations in CTNNB1 are particularly common, occurring in approximately 50% of low-grade endometrioid ovarian cancers." (PMID 32679669, 2020). "PTEN mutations are characteristic for endometrioid ovarian cancer (EnOC) and ovarian clear cell carcinoma (OCCC), while CTNNB1 is characteristic for endometrioid ovarian cancer (EnOC)." (PMID 38391958, 2024). "In mouse ovarian endometrioid adenocarcinomas (OEAs) arising from Apc- and Pten-inactivation, while Ctnnb1 hemizygous dose affected β-catenin levels and some β-catenin/TCF target genes, Myc induction was retained and OEAs arose in a fashion akin to that seen with intact Ctnnb1 gene dose." (PMID 26528816, 2015). "In contrast, Ctnnb1 hemizygous inactivation does not affect mouse ovarian endometrioid adenocarcinoma development arising from Apc- and Pten-inactivation." (PMID 26528816, 2015).
ovarian endometrioid carcinoma (11 papers, 2015 to 2025). "We observed a weak association between CTNNB1 mutation status and survival in individuals with ovarian endometrioid carcinomas (P = 0.05)." (PMID 40981433, 2025). "Mutations in CTNNB1 are found in around 43% of endometrioid ovarian carcinomas leading to a loss of β-catenin expression in 51% of cases." (PMID 36982928, 2023). "which was consistent with previous study that PTEN and CTNNB1 mutations were significantly different in low-grade ovarian endometrioid carcinomas and low-grade endometrial endometrioid carcinomas." (PMID 34837690, 2021). "In contrast, CTNNB1 mutations are significantly different in low-grade ovarian endometrioid carcinomas (53%) compared to 28% of the low-grade endometrial endometrioid carcinomas." (PMID 28103826, 2017). "We also studied the consequences of shRNA-mediated inhibition of CTNNB1 on MYC gene expression in the TOV112D human ovarian endometrioid carcinoma cell line that harbors a CTNNB1 oncogenic mutation leading to β-catenin/TCF dysregulation." (PMID 26528816, 2015).
adrenal tumor (10 papers, 2016 to 2025). "The genetic analysis of the present adrenal tumor revealed a somatic mutation p.Ser45Ala of the CTNNB1-gene." (PMID 34489873, 2021). "Researchers have found that the expression level of ISM1 was significantly upregulated in both CTNNB1 mutated adrenal tumors and CTNNB1 mutated adrenal lesions, suggesting that ISM1 may be a potential therapeutic target for CTNNB1 mutation-related adrenal disease." (PMID 35958402, 2022). "To investigate the pathways activated in the double mutants we performed RNA-seq on RNA derived from adrenal tumours from 3-month-old Ctnnb1 and double-mutant female and male mutant mice." (PMID 33214683, 2021). "Transgenic overexpression of Hoxb9 in the adrenal cortex of mice with activated Ctnnb1 led to larger adrenal tumours." (PMID 33214683, 2021). "Adrenal tumours from double-mutant mice expressed higher levels of Hoxb9 mRNA and protein than single Ctnnb1 mutants, confirming expression of the transgene." (PMID 33214683, 2021). "Nevertheless, we were able to identify differentially expressed genes previously reported in other types of adrenal tumours with CTNNB1-mtations, and validated two of these using RT-PCR." (PMID 31000732, 2019). "Somatic mutations that constitutively activate WNT/β-catenin (CTNNB1), G-protein (GNAS, GNAQ, GNA11), and cAMP/protein kinase A (PKA) (GNAS, PRKACA) signaling can drive unrestrained cell proliferation and survival in diverse tumors, including adrenal tumors." (PMID 36004349, 2022). "However, it has been shown that GNAS and CTNNB1 mutations are not always mutually exclusive in CPAs, and that mutations of CTNNB1 are also present in non-secreting adrenal tumors." (PMID 27445978, 2016).
endometrioid endometrial carcinomas (10 papers, 2010 to 2023). "CTNNB1 mutation is significantly associated with recurrence in early stage endometrioid endometrial carcinomas, especially in the NSMP, appearing potentially useful in directing adjuvant treatment." (PMID 35034160, 2022). "Electronic databases were searched from their inception to November 2020 for all studies assessing the prognostic value of CTNNB1 mutation in early stage (FIGO I–II) endometrioid endometrial carcinoma." (PMID 35034160, 2022). "Mutations in exon 3 of CTNNB1 result in stabilization of a protein that resists degradation, leading to nuclear accumulation of β-catenin, have been described in endometrioid endometrial carcinoma." (PMID 20368795, 2010). "The reported frequency of CTNNB1 mutations in endometrioid endometrial carcinoma ranges from 14–44%." (PMID 20368795, 2010). "Similarly, 18% of endometrioid endometrial carcinomas also possess CTNNB1 mutations." (PMID 36982928, 2023). "25–30% of the endometrial MLA cases harbor additional mutational events within the PTEN-, CTNNB1-, and ARID1A-genes which are also common mutational alterations in endometrioid endometrial carcinomas." (PMID 37668797, 2023). "In the last years, mutations in the exon 3 of CTNNB1 have emerged as a possible prognostic factor for recurrence in early stage endometrioid endometrial carcinoma, especially in cases with no specific molecular profile (NSMP)." (PMID 35034160, 2022). "Furthermore, none of the five main alterations of endometrioid endometrial carcinoma (mutations of PTEN, PIK3CA, KRAS, and CTNNB1 genes and MSI) plays a major role in non-endometrioid endometrial carcinoma." (PMID 20368795, 2010).
multiple myeloma (10 papers, 2017 to 2022). "In the case of multiple myeloma, the AA-genotype of the CTNNB1 gene (that encodes for catenin beta 1) correlated with an increased response to dexamethasone, cyclophosphamide, and thalidomide treatment in comparison with GG and AG genotypes." (PMID 34086487, 2021). "Another example of signaling crosstalk identified by this analysis is that of YAP1_CTNNB1 interactions in L363 myeloma cells (94%ile), CADO-ES1 Ewing’s sarcoma cells (96%ile), and A204 rhabdomyosarcoma cells (96%ile)." (PMID 28118365, 2017). "This is in contrast to previous studies that showed efficacy of BC2059 in multiple myeloma and acute myeloid leukemia, tumors that typically have a upregulated Wnt/β-catenin pathway, but are not mutated for the CTNNB1 gene." (PMID 36240209, 2022). "Since CTNNB1 has been shown to contribute to apoptosis resistance in multiple myeloma cells, it is possible that BCNHL’s decreased ability to destroy CTNNB1 in may contribute to a similar pathogenic mechanism." (PMID 36873459, 2022). "On the other hand, no predisposing role of any CTNNB1 (rs4135385) polymorphism could be confirmed in terms of multiple myeloma." (PMID 31506802, 2020). "Overexpression of CSNK1A1 can promote the proliferation and survival of tumor cells by downregulating the expression of CTNNB1 in myeloma; CSNK1A1 and CTNNB1 both function in the classic Wnt/β-catenin signaling pathway." (PMID 32993576, 2020).
Adamantinomatous Craniopharyngioma (9 papers, 2013 to 2026). A craniopharyngioma consisting of broad strands, cords and bridges of a multistratified squamous epithelium with peripheral palisading of nuclei. "6–8 Loss of this tumor suppressor gene leads to constitutive activation of the Wnt signaling pathway, similar to the observed downstream effects of activating CTNNB1 mutations in adamantinomatous craniopharyngioma." (PMID 34549183, 2021). "One patient had a mutation in the WNT pathway, specifically a missense mutation in CTNNB1 typically associated with adamantinomatous craniopharyngiomas." (PMID 31712784, 2019). "Mutation in the exon 3 of the CTNNB1 gene that codifies the binding site for the degradation complex of the β-catenin molecule is one of the molecular findings associated with adamantinomatous craniopharyngiomas." (PMID 23638078, 2013). "In addition, they play a critical role in tumor formation, specifically in the etiology of human adamantinomatous craniopharyngioma, a clinically relevant tumor that is associated with mutations in CTNNB1 (gene encoding β‐catenin)." (PMID 26763580, 2016). "Taken together, this case demonstrates that adamantinomatous craniopharyngiomas, typically driven by proto-oncogenic CTNNB1 mutations, may also arise independently from loss of the tumor suppressor gene APC, leading to similar downstream constitutive activation of the Wnt signaling pathway." (PMID 34549183, 2021). "In contrast, adamantinomatous craniopharyngioma (ACP), characterized by CTNNB1 mutations and a cystic phenotype with a prominent inflammatory microenvironment, lacks a single actionable oncogenic driver." (PMID 41898146, 2026). "Identification of specific molecular driver mutations in each type- BRAF V600E in papillary craniopharyngiomas (PCP) and CTNNB1 in adamantinomatous craniopharyngiomas (ACP) has resulted in a paradigm shift in the management of adult CPs." (PMID 39634188, 2024). "In this report, we describe the first case, to our knowledge, of adamantinomatous craniopharyngioma arising from somatic loss of APC in the absence of germline mutations or a CTNNB1 mutation." (PMID 34549183, 2021).
bladder cancer (9 papers, 2016 to 2023). "Recent studies have suggested that CTNNB1 hyperactivation is closely related to the occurrence and development of bladder cancer (BCa)." (PMID 37740194, 2023). "In summary, Uchl3 tends to facilitate bladder cancer progression by stabilizing CTNNB1 and promoting WNT pathway activity in vivo." (PMID 37740194, 2023). "In a related study, miR-3619-5p overexpression in bladder cancer was shown to inhibit tumorigenesis by targeting the CTNNB1 3′-UTR and inhibiting β-catenin expression." (PMID 32983239, 2020). "However, whether UCHL3 is involved in the deubiquitination of CTNNB1 and its role in bladder cancer remain unknown." (PMID 37740194, 2023). "In several bladder cancer cell lines, high levels of UCHL3 protein were accompanied by high levels of CTNNB1 protein." (PMID 37740194, 2023).
brain tumor (9 papers, 2015 to 2025). "Additionally, stabilizing CTNNB1 mutations activating the WNT pathway have been reported in brain tumors with LIN28A overexpression." (PMID 40680886, 2025). "The oncogenic proteins LIN28A and CTNNB1 have been reported in embryonic brain tumors." (PMID 40680886, 2025). "According to reports, CTNNB1 belongs to Wnt signal pathway and is mutated in patients of lung metastasis to brain, but few or no mutations were described in original brain tumor specimens." (PMID 34642306, 2021). "To compare the data quality of RRST and standard Visium datasets obtained from the pediatric brain tumor samples, we examined the expression of WNT-signaling genes, including AXIN2, DKK4, LEF1 and CTNNB1 and two known targets of the WNT pathway SP5, GAD122,23." (PMID 36720873, 2023).
developmental delay (9 papers, 2017 to 2025). "In this study, we identified mutations in CTNNB1 using next-generation sequencing (NGS) in two patients with developmental delays who presented to the outpatient clinic." (PMID 39935833, 2025). "This study aimed to identify CTNNB1 mutations in two patients presenting with global developmental delay and compare their distinct phenotypes." (PMID 39935833, 2025). "However, no specific description of retinopathy in this condition was published until 2016, when a child with developmental delay who had a known disruptive variant in CTNNB1 was also found to have familial exudative vitreoretinopathy (FEVR) and retinal detachment." (PMID 33350591, 2021). "However, one 3-year-old Chinese boy initially presented with EVR showed facial dysmorphism and global developmental delay during follow-up and WES identified a de novo 1-bp insertion (c.1434_1435insC, Glu479ArgfsTer18) in CTNNB1 gene (OMIM *116806.0023)." (PMID 30929091, 2019).
sarcoma (9 papers, 2015 to 2025). A usually aggressive malignant neoplasm of the soft tissue or bone. "It was found that sarcomas O-P2, L-P5, and Rm-P6 carry mutations in the CTNNB1 (gene accession number: NG_013302.2), KIT (gene accession number: NG_007456.1), and NF2 (gene accession number: NG_009057.1) genes." (PMID 41300532, 2025). "Pseudoendocrine sarcoma is a rare, recently described intermediate grade sarcoma of uncertain phenotype that most commonly affects the paraspinal location in older patients with a distinctive endocrine/paraganglioma-like morphology and unique CTNNB1 point mutation." (PMID 39093425, 2025). "Our cohort also included two sarcomas with VIM–KMT2A fusions, each harboring concurrent mutations in CTNNB1, SMARCB1, and ARID1A and characterized histologically by sheets of spindle-to-round blue cells." (PMID 32461620, 2020). "In summary, our work shows that EMX1 and EMX2 act as tumor suppressors by suppressing the activity of stem cell regulatory genes (OSKM, NANOG, and PROM1) and effectors of the canonical Wnt pathway (CTNNB1, TCF4, MYC, WNT1 and CCDN1) in sarcoma." (PMID 34364391, 2021).
serous carcinoma (9 papers, 2016 to 2025). "ID8 cells also lack other mutations typical of clear cell carcinoma (Arid1a, Pik3ca), low-grade serous carcinoma (Braf), endometrioid (Ctnnb1), or mucinous (Kras) carcinomas." (PMID 29927933, 2018).
type 2 diabetes (9 papers, 2014 to 2026). "According to the literature study, some genes that are associated with developmental dyslexia, such as ROBO1, DCDC2, DYX1C1, and KIA0319, and some genes that are associated with type 2 diabetes CTNNB1, TCF7L2, and KIF3A had shown some connections with each other." (PMID 34674647, 2021). "From these evidences, we could make hypothesis that type 2 diabetes is caused by a decrement of glucose import because activation of CTNNB1 is inhibited by lower expression of AXIN1." (PMID 27490120, 2016). "TF network analysis uncovered four upstream hub transcriptional factors NF-κB, ESR1, STAT3 and CTNNB1 active in both type 2 diabetes and hIAPP islets." (PMID 34554282, 2022). "Key mediators of the injury responses in islets transgenic for human IAPP or those from individuals with type 2 diabetes include STAT3, NF-κB, ESR1 and CTNNB1 by transcription factor analysis and COL3A1, NID1 and ZNF800 by gene regulatory network analysis." (PMID 34554282, 2022).
viral infection (9 papers, 2011 to 2025). "Furthermore, a significant correlation was observed between CTNNB1 mutations and hepatitis virus infections (p < 0.01), reinforcing the potential role of viral infections in Wnt/β‐catenin pathway activation." (PMID 40344393, 2025). "WNT modulates the secretion of IFN-β through the CTNNB1 pathway during viral infection, while knockdown of CTNNB1 notably increased secretion of IFN-β protein." (PMID 38734674, 2024). "WNT2B and WNT9B secretion in response to viral infection induce a CTNNB1-dependent signaling pathway leading to decreased magnitude of IFNB1 production and effector response in a feedback inhibition mechanism." (PMID 23785285, 2013). "Altogether, these results confirm the role of a canonical-like WNT/GSK3/CTNNB1 pathway in a negative regulation of innate immunity upon viral infections of primary human cells including immune cells." (PMID 23785285, 2013). "More importantly, we demonstrated for the first time the feedback inhibition of the RLR/MAVS/IRF3-mediated antiviral innate response by activation of WNT/CTNNB1 pathway induced upon viral infection." (PMID 23785285, 2013). "Coherently, we found that viral infection induces the accumulation of an active form of CTNNB1 and that CTNNB1 gene silencing increases SeV-induced IFNB1, IFIT1 and TNF expression, as well as NFKBIA (IκBα) phosphorylation at serine 32 (P-Ser32) to release NF-κB inhibition." (PMID 23785285, 2013). "Here we show that secretion of WNT2B and WNT9B and stabilization of β-catenin (CTNNB1) upon virus infection negatively regulate expression of representative inducible genes IFNB1, IFIT1 and TNF in a CTNNB1-dependent effector mechanism." (PMID 23785285, 2013). "Finally, in addition to SeV infection, the contribution of GSK3/CTNNB1 in feedback inhibition of innate immunity was further extended to HCV infection of primary human hepatocytes, suggesting a regulatory role in various types of viral infections." (PMID 23785285, 2013).
acinar cell carcinoma (8 papers, 2015 to 2022). "A mutation unique to DSL-6A/C1 is Ctnnb1, a reported gene in 20–25% of human acinar cell carcinomas." (PMID 29925311, 2018). "Whole exome sequencing of coincident ductal and acinar carcinomas suggest they are derived from a common progenitor, with prognostic divergence possibly driven by varied accumulation of PTEN or CTNNB1 alterations." (PMID 35474657, 2021).